ERCC6L2 (ERCC excision repair 6 like 2)
Description:
Promotes double-strand break (DSB) end-joining and facilitates programmed recombination by controlling how DNA ends are joined in a spatially oriented manner during repair (By similarity). Also plays a role in DNA repair by restricting DNA end resection in double strand break (DSB) repair. Facilitates replication of complex DNA regions and regulates the maintenance of chromatin structure.
Synonyms: C9orf102; RAD26L; FLJ37706; HEBO; BMFS2; SR278
Tractability: PROTAC: ubiquitination databases record sites on it.
Gene: Protein-coding gene on chromosome 9 (95,871,264 to 96,121,154, forward strand). Ensembl gene ENSG00000182150.
Subcellular location: Nucleus; Cytoplasm, cytoskeleton, microtubule organizing center, centrosome; Mitochondrion; Chromosome, centromere
Subcellular location (Human Protein Atlas): Cytosol; Nucleoplasm
Gene Ontology:
Molecular function: protein binding; protein kinase binding; ATP binding
Biological process: cellular response to reactive oxygen species; DNA damage response; double-strand break repair via classical nonhomologous end joining; interstrand cross-link repair
Cellular component: centrosome; chromosome, centromeric region; cytoplasm; mitochondrion; nucleoplasm; nucleus; protein-containing complex
Genetic constraint (gnomAD): Loss-of-function variants: 63 observed, 98.08 expected, observed/expected ratio (o/e) 0.64, 90% interval 0.52 to 0.79. The upper end of that interval is the gene's LOEUF score, 0.79, which puts it in group 3 of 6, group 1 being the genes least tolerant of losing a copy. Missense variants: 1,401 observed, 1,658.6 expected, observed/expected ratio (o/e) 0.84, 90% interval 0.81 to 0.88. Synonymous variants: 522 observed, 575.48 expected, observed/expected ratio (o/e) 0.91, 90% interval 0.84 to 0.98.
Homologues: Orthologues: macaque ERCC6L2 (93% identical), dog ERCC6L2 (81% identical), pig ERCC6L2 (80% identical).
Diseases named in the same sentence as ERCC6L2 in open-access papers:
ERCC6L2 is named in the same sentence as 36 diseases in open-access papers, as found by Europe PMC text mining. Sharing a sentence is not in itself a finding about the gene and the disease. The quoted sentences say what the papers report.
bone marrow failure (7 papers, 2022 to 2026). "Although HLH has been reported in patients with adenosine deaminase 2 (ADA2) deficiency, to date it has not been reported in individuals harboring pathogenic variants in ERCC6L2, a gene typically linked to inherited bone marrow failure." (PMID 41710027, 2026). "To date, more than 50 patients with bi-allelic ERCC6L2 mutations and bone marrow failure have been reported in the literature." (PMID 39906419, 2025). "Biallelic LoF variants in the ERCC6L2 gene, including homozygous c.1424del p.(Ile475ThrfsTer36) (previously known as c.1457del), have been described in patients with inherited bone marrow failure and acute myeloid leukaemia." (PMID 38036545, 2023). "Homozygous germline loss‐of‐function ERCC excision repair 6 like 2 (ERCC6L2) variants were first reported in two unrelated cases of bone marrow failure (BMF) with developmental delay and microcephaly." (PMID 36156210, 2022). "ERCC6L2 (Excision Repair Cross-Complementation Group 6 Like 2), also known as RAD26L and as the HElicase mutated in Bone Marrow Failure, HEBO24 is a poorly characterized member of the Sucrose Non-Fermenting 2 (SNF2) family of ATPases25 associated with a distinct bone marrow failure syndrome." (PMID 37014751, 2023). "Likewise, ERCC6L2, a gene mutated in MDS and leukaemia that is associated with bone marrow failure, was identified as a new NHEJ factor recruited to chromatin after IR promoting DNA end-joining independent of the 53BP1-RIF1-shieldin pathway." (PMID 36980782, 2023).
bone marrow failure syndrome (7 papers, 2018 to 2026). "ERCC6L2 disease (ED) is a rare bone marrow failure syndrome caused by biallelic germline mutations in ERCC6L2." (PMID 42311431, 2026). "Mounting evidence links ERCC6L2 to a distinct inherited bone marrow failure syndrome (IBMFS) that includes developmental delay, microcephaly, and predisposition to cancer." (PMID 37014751, 2023).
Fanconi anemia (4 papers, 2020 to 2024). Fanconi anemia (FA) is a hereditary DNA repair disorder characterized by progressive pancytopenia with bone marrow failure, variable congenital malformations and predisposition to develop hematological or solid tumors. "Further disorders include Fanconi anemia and rare entities, including mutations in DNAJC21 and ERCC6L2." (PMID 33097095, 2020). "While our understanding of ERCC6L2‐mediated predisposition to myeloid disease is still evolving, the link between impaired DNA damage repair factors and inherited BMF syndromes is already well established and drives the phenotype of Fanconi anaemia (FA) and DNA Ligase IV Deficiency syndrome." (PMID 36156210, 2022).
acute myeloid leukemia (3 papers, 2022 to 2025). Acute myeloid leukemia (AML) is a group of neoplasms arising from precursor cells committed to the myeloid cell-line differentiation. "While germline mutations in the DNA repair factor ERCC excision repair 6 like 2 (ERCC6L2) give rise to bone marrow failure and acute myeloid leukaemia, their consequences on normal haematopoiesis remain unclear." (PMID 36156210, 2022).
leukaemia (3 papers, 2018 to 2023). "It is possible that the loss of ERCC6L2 induces a stress on erythroid progenitors that fosters the acquisition of secondary mutations and contributes to the erythroid leukaemia phenotype observed in ERCC6L2‐deficient patients." (PMID 36156210, 2022). "Myelodysplastic syndrome and leukemia were not reported among the six patients; however, due to the small series and the predicted functions of ERCC6L2, it is reasonable to manage these patients with a leukemia surveillance program until a leukemic risk is confidently excluded." (PMID 29633571, 2018). "Hence, inclusion of ERCC6L2 in the list of genes to be tested when the features described in the present manuscript are encountered may be the only tool that allows for early institution of a leukemia‐surveillance program." (PMID 29633571, 2018).
myelodysplastic syndrome (3 papers, 2018 to 2023). A clonal hematopoietic disorder characterized by dysplasia and ineffective hematopoiesis in one or more of the hematopoietic cell lines. "Interestingly, preliminary results from Spanish Group of Myelodysplastic Syndrome (GESMD) showed a high rate of heterozygous ERCC6L2 mutations in a cohort of adult MDS suggesting a potential role for heterozygous configuration in MDS onset." (PMID 36790458, 2023).
acute erythroid leukemia (2 papers, 2020 to 2023). An acute myeloid leukemia characterized by a predominant immature erythroid population. "Biallelic loss-of-function mutations in ERCC6 like 2 (ERCC6L2) have been associated with BMF, MDS, and acute erythroid leukemia (AML M6)." (PMID 33194896, 2020). "Several patients with acute erythroid leukemia have been reported, either progressing from MDS or as isolated disease, leading to the assumption that this AML subtype seems to be much more prevalent in ERCC6L2 germline-mutated patients." (PMID 37091189, 2023). "The prognosis of MDS/AML in patients with ERCC6L2 germline variants is poor, especially when progression to acute erythroid leukemia is noted, with no known survivors of this AML subtype so far." (PMID 37091189, 2023).
Anxiety (2 papers, 2023 to 2025). Intense feelings of nervousness, tension, or panic often arise in response to interpersonal stresses. "For high anxiety state assessment across all subjects in the independent test cohort, the best biomarker was ERCC6L2, decreased in expression in high anxiety, with an AUC of 68 % (p = 0.004) cross-sectionally, and an AUC of 69% (p = 0.03) longitudinally." (PMID 36878964, 2023). "ERCC6L2 also has an AUC of 100% (p = 0.0007) longitudinally for clinical anxiety in males with depression." (PMID 36878964, 2023).
anxiety disorder (1 paper, 2023). A category of psychiatric disorders which are characterized by anxious feelings or fear often accompanied by physical symptoms associated with anxiety. "ERCC6L2 (ERCC Excision Repair 6 Like 2) is a novel gene for anxiety disorders, with no prior evidence of involvement in the literature." (PMID 36878964, 2023).
ataxia telangiectasia (1 paper, 2020). Ataxia-telangiectasia is the association of severe combined immunodeficiency (affecting mainly the humoral immune response) with progressive cerebellar ataxia. "These clinical entities include xeroderma pigmentosum, constitutional mismatch repair deficiency, ataxia telangiectasia, Nijmegen breakage syndrome, deficiencies of DNA ligase IV, NHEJ/Cernunnos, and ERCC6L2, as well as Bloom, Werner, and Rothmund-Thompson syndromes." (PMID 33194896, 2020).
Cockayne Syndrome B (1 paper, 2022). "ERCC6L2 has 30% identity to ERCC6 at the protein level, the causal gene for Cockayne Syndrome B (CSB)." (PMID 35812759, 2022).
lung carcinoma (1 paper, 2018). "Knockdown of ERCC6L2 genes in lung cancer cells showed an increase in DNA damage and intracellular ROS." (PMID 29633571, 2018).
Neurodevelopmental delay (1 paper, 2025). "The ERCC6L2-associated disease has been so far frequently related to neurodevelopmental delay and consanguinity and recognized as a predisposition syndrome to myeloid malignancies." (PMID 39906419, 2025).
Obesity (1 paper, 2022). Accumulation of substantial excess body fat. "Taken together, the newly identified mutation in Ercc6l2 emerges as the best candidate variant underlying the obesity and metabolic phenotypes in the LH17LNa strain." (PMID 35812759, 2022). "The discovery of the significance of Ercc6l2 in the context of female-specific adipocyte biology could represent a novel role of DNA repair failure syndromes in obesity pathogenesis." (PMID 35812759, 2022).
cancer (5 papers, 2018 to 2023). A tumor composed of atypical neoplastic, often pleomorphic cells that invade other tissues. "This patient was identified to have a missense VUS with a high score of pathogenic prediction in the ERCC6L2 and SIK3 cancer-related genes in addition to VUS in the SMAD6 CRC-related gene." (PMID 36077770, 2022). "ERCC6L2 (↑2.9X twins) is excision-repair like 2, which has known relevance in cancer, but is difficult to connect with ADHD." (PMID 33115496, 2020).
hematologic malignancies (3 papers, 2020 to 2025). "The aim of this review is to summarize the molecular properties of ERCC6L2 and the association between germline ERCC6L2 mutations and hematological diseases." (PMID 36790458, 2023). "The ERCC6L2-related hematological disease presents a high penetrance, posing important questions regarding the treatment strategies and possible preemptive approaches." (PMID 36790458, 2023). "Segregation analysis revealed one sibling with bi-allelic ERCC6L2 variants without a previous diagnosis of hematological disorder." (PMID 39906419, 2025).
tumor (1 paper, 2024). "Conversely, ERCC4 and ERCC6L2 displayed distinct correlation patterns compared to ERCC6L and the other three genes, suggesting their tumor-suppressing function." (PMID 39582530, 2024).
ERCC6L2 also shares sentences with these, for which no sentence is quoted: developmental delay (4 papers); microcephaly (4); depression (2); Shwachman-Diamond syndrome (2); acute lymphoblastic leukemia (1); basal cell carcinoma (1); brain tumors (1); Diamond-Blackfan anemia (1); dyskeratosis congenita (1); hematologic cancer (1); hemophagocytic lymphohistiocytosis (1); hyperparathyroidism (1); inherited bone marrow failure syndrome (1); myeloid malignancies (1); Nijmegen breakage syndrome (1); parathyroid carcinoma (1); retinitis pigmentosa (1); rhabdomyosarcoma (1); xeroderma pigmentosum (1).